BCL2 (BCL2 apoptosis regulator)
Diseases named in the same sentence as BCL2 in open-access papers (continued):
Sharing a sentence is not in itself a finding about the gene and the disease.
infection (continued). "Compared to the uninfected controls, the coinfected samples showed an upregulated expression of bcl2 at 12 hpi in the infection models III and IV in comparison to uninfected control, whereas a higher expression of bcl2 was observed in infection-IV." (PMID 34585958, 2021). "Bcl-2 can act as an antagonist to cell death, and in late infection, it is pro-apoptotic by decreasing Bcl-2." (PMID 34867371, 2021). "We found that IAV-infection increased the ratio of Bax/Bcl-2, while 3D treatment reduced this upregulation of Bax and Bcl-2 in A549 cells." (PMID 33670217, 2021). "Expression of BCL-2 increases during infection and increase further after Sch B treatment, which is expected to happen as it inhibits the activation of apoptotic caspases." (PMID 34161342, 2021). "After inhibiting Wnt/β-catenin signaling pathway by inhibitor IWP2, the Bcl2/Bax ratio in the inhibited cells decreased (P<0.05) upon Ct infection." (PMID 34568091, 2021). "Numerous viruses have evolved sophisticated countermeasures to hijack the early programmed cell death of host cells in response to infection, including the use of proteins homologous in sequence or structure to Bcl-2." (PMID 34372579, 2021). "In Tulahuen strain infection, IL-6/pSTAT3 protects cardiomyocytes through upregulation of anti-apoptotic factor Bcl-2, thus maintaining the survival of the host cell that is beneficial for parasite persistence." (PMID 32626662, 2020). "Following the sharp expansion upon pathogen infection, most T cells die in order to keep balance in the immune system, a process which is controlled by death receptors during the early phase and Bcl-2 proteins in the later phase." (PMID 31919392, 2020). "It sounds plausible to suggest that the Wt1-5 infection can contribute to Bax activation through the decrease in the Bax/Bcl-2 complex number in the mitochondrial membrane." (PMID 32722005, 2020). "Together, these data suggest that viral production (monitored by p24 expression) occurs more frequently in BCL2+ cells than BCL2- cells despite a similar frequency of infection (HIV DNA)." (PMID 33075109, 2020). "Analysis of Kbm139+ populations on day 7 after infection revealed that for both days 3 and 6 of Bcl-2 inhibition, an increase of the overall affinity of the WT cell pool was induced, which was not the case for EomesCKO cells." (PMID 32182234, 2020). "In PBMO, inhibition of EGFR abolished both AREG- and infection-induced increases in intracellular Bcl-2 levels; however, in CBMO, it did only suppress the increase which was mediated by stimulation with AREG." (PMID 32082070, 2019). "In contrast, administration of yogurt or probiotics prior- and post-infection with S. mansoni possessed a significant increase in the expression level of the pro-apoptotic Bcl-2 and a significant decrease in the expression level of Bax." (PMID 30606163, 2019). "At day 2 post infection, we observed even higher proliferation and expression of the survival marker Bcl2 but comparable apoptosis in Tbx21−/− SMARTA TFH cells compared to WT cells." (PMID 30984183, 2019). "From 12h to 72h post-infection, the levels of Caspase-3, Caspase-9 and Bax proteins, and Bax/Bcl-2 protein ratio in the lean-E." (PMID 31085802, 2019). "At day 8 post infection, higher apoptosis rates and lower Bcl2 expression were found in Tbx21−/− SMARTA TFH cells than in WT cells." (PMID 30984183, 2019). "We also found that FYC and its main components inhibited the expression of BAX induced by infection and increased the expression of Bcl-2." (PMID 31312226, 2019). "The protein expression levels of Caspase-3 and Bax, and Bax/Bcl-2 protein ratio in the DIO group were higher (p<0.05) than those in the lean group before infection." (PMID 31085802, 2019).
infection (continued). "The present study shows that JEV slowly stimulated the expression of Bcl-2 protein during the early period of infection." (PMID 31658698, 2019). "The Caspase-3 mRNA and Bax/Bcl-2 mRNA ratio of the DIO group were significantly higher (p<0.05) than those of the lean group before infection." (PMID 31085802, 2019). "A study also suggested that apoptosis induced by RHDV-infection is related to the modulation of Bcl2 and Bax genes." (PMID 30687286, 2018). "The result is consistent with a previous study reporting that the anti-apoptotic protein Bcl-2 was down-regulated in the human mononuclear phagocytes after an infection with Mycobacterium bovis BCG." (PMID 30112141, 2018). "In this study, we examined the roles of BCL2 proteins in the induction of apoptosis in cells upon infection with flaviviruses, such as Japanese encephalitis virus, Dengue virus and Zika virus." (PMID 30261081, 2018). "The increased expression of BCL2 observed in porcine MLN after infection is also in accordance with the ability of Salmonella to prevent apoptosis, as a strategy to provide survival advantage inside host cells." (PMID 29391047, 2018). "In ECs, infection with P. gingivalis displayed anti-apoptotic effects through a decrease of Bax-1 and Apaf-1 and an increase of anti-apoptotic Bcl-2 expression in EC." (PMID 30297793, 2018). "Viral regulation of Mcl-1 and Bcl-2 expression allows for strict control over caspase function during infection, allowing the virus to not only control cell survival, but also direct monocyte-to-macrophage differentiation." (PMID 30274264, 2018). "The levels of caspase 3 and Bax were also increased, and Bcl-2 was decreased by CA16 infection, indicating apoptosis was induced in brain." (PMID 30186868, 2018). "The expression levels of apoptosis-related proteins were examined by Western Blot; caspase-3, caspase-8, and caspase-9 activation and Bcl-2/Bax levels in A549 cells were assessed following infection with rL-RVG or NDV and treatment with MLA and ACB." (PMID 28974241, 2017). "Over the same infection time course, both BCL-2 and BFL-1 were initially downregulated in early proliferating B cells relative to uninfected B cells, then upregulated during LCL outgrowth." (PMID 28425914, 2017). "Conversely, during the late stages of infection, the development of polypide can inhibit Bcl-2 expression and increase Bax expression, which promotes MPTP opening and further induces cell apoptosis." (PMID 29282063, 2017). "The levels of pro-apoptotic member Bax increased as a function of time after infection, while decreased the levels of anti-apoptotic members such as Bcl-2 and Bcl-XL." (PMID 29042667, 2017). "Upon infection, the intracellular amounts of anti-apoptotic Bcl2 are significantly elevated in the DP3 cells." (PMID 28091621, 2017). "The levels of pro-apoptotic member Bax increased as a function of time after infection, while decreased the levels of anti-apoptotic members such as Bcl-2 and Bcl-XL 6,8." (PMID 29042667, 2017). "HpSS1 infection significantly induced down-regulation of Bcl-2 and up-regulation of Bax expression, which were inhibited by Z-DEVD-FMK." (PMID 28938629, 2017). "From 12 h until the end of the infection, we observed a significant Bax/Bcl-2 ratio which was significantly diminished by MG-132 (P < 0.05 and P < 0.01)." (PMID 29042667, 2017). "Infection with Ft SchuS4 resulted in significant changes in both antiapoptotic (Bax/Bcl-2, Mcl-1, Bcl-xl, and Bcl-xl/Bak) and proapoptotic markers (Bax, Bak, Bim, and caspase-3)." (PMID 28955505, 2017). "Significantly lesser induction of Bcl-2 was observed when TLR-2 was downregulated by siRNA transfection prior to infection." (PMID 27826299, 2016). "Both of these pathogens target multiple cell death pathways in myeloid cells, and the expression of bcl2 resulted in decreased PCD after infection." (PMID 27973535, 2016).
infection (continued). "CD68(bcl2)tg mice infected with L. pneumophila had significantly increased damage in their lungs compared to littermate controls as soon as 48 hours after infection and this damage was even greater 96 hours after infection in transgenic mice." (PMID 27973535, 2016). "In both cell subsets, there was an overall decrease in Bcl2 expression at 7 days post infection compared to prior to infection, but to a greater extent for CD38+ CD4+ T cells." (PMID 27662621, 2016). "Given the increase in different myeloid cell types during infection with S. pyogenes in CD68(bcl2)tg mice, the effect of ectopic expression of bcl2 on S. pyogenes-induced cell death was examined." (PMID 27973535, 2016). "The cell death prevented by bcl-2 during infection was largely apoptotic, as indicated by caspase-3/7 activation and cell permeability." (PMID 27973535, 2016). "In summary, this part of the data showed participation of MEK/ERK signaling pathway in L. donovani-induced increases in Bcl-2 levels, lowering of NO production and higher infection rates." (PMID 27826299, 2016). "Collectively, our study for the first time reveals a pro-parasitic role of host Bcl-2 and the capacity of host-derived IL-13 to modulate NO levels during infection via Bcl-2." (PMID 27826299, 2016). "Wild-type mPM showed a gradual increase in TLR-2 expression post infection with an increase in Bcl-2 levels." (PMID 27826299, 2016). "Mice constitutively expressing bcl-2 in myeloid cells had decreased survival after infection with S. pyogenes." (PMID 27973535, 2016). "Inhibition of ERK 1/2 phosphorylation with U0126 resulted in an observable reduction in the infection-induced Bcl-2 increase." (PMID 27826299, 2016). "While there is a mild increase in bacterial load in lungs of infected CD68(bcl2)tg mice 96 hours after infection, the increased inflammation precedes this increase in bacterial burden." (PMID 27973535, 2016). "Similar to THP-1 MDM, hMDM showed an increase in TLR-2 expression post infection, and TLR-2 downregulation prior to infection prevented the increase in Bcl-2 levels." (PMID 27826299, 2016). "Diminution of infection on Bcl-2 inhibition provides an opportunity for using Bcl-2 as an antileishmanial target." (PMID 27826299, 2016). "In order to determine if this increased lung damage was due to an increased bacterial burden in the lung of CD68(bcl2)tg mice we determined the colony forming units (CFUs) in the lungs from infected mice 1 hours, 48 hours, and 96 hours after infection." (PMID 27973535, 2016). "The siRNA-mediated downregulation of Bcl-2 in hMDM also resulted in lesser infection rates as compared to scrambled siRNA-treated cells." (PMID 27826299, 2016). "The degree of basal Bcl-2 expression after overnight culture was lower in IH-CD8+ T-cells compared to blood-derived CD8+ T-cells in HCV mono-infection." (PMID 27315061, 2016). "We found activation of both of these molecules at early stages during infection; however, only the latter was found to mediate Leishmania-induced Bcl-2 expression." (PMID 27826299, 2016). "Downregulation of post infection Bcl-2 increase using siRNA or functional inhibition using Bcl-2 small molecule inhibitors interfered with intracellular parasite survival confirming the necessity of elevated Bcl-2 during infection." (PMID 27826299, 2016). "Infection with Pg increased significantly caspase-3, -9, Bax-1 and Apaf-1 expression and decreased Bcl-2 expression in comparison with Ox-LDL pre-treated cells." (PMID 27124409, 2016). "In all, the data suggested that infection-induced induction of Bcl-2 was predominantly mediated through STAT-3." (PMID 27826299, 2016). "After infection CD68(bcl2)tg mice lose more weight and have a longer recovery time when compared to littermate controls." (PMID 27973535, 2016). "There was a significant increase in infiltrating cells into the peritoneal cavity of CD68(bcl2)tg mice 24 hours after infection with S. pyogenes." (PMID 27973535, 2016).
infection (continued). "Clearly, MEK/ERK acted as the downstream effectors of TLR-2 after infection with the L. donovani parasite leading to Bcl-2 increase favoring parasite survival." (PMID 27826299, 2016). "Our results showed significantly increased iNOS activity during infection, when either Bcl-2 expression or function was inhibited, suggesting an inhibitory role of Bcl-2 on NO production." (PMID 27826299, 2016). "Given the impact that the CD68(bcl2)tg has on in vivo infection with L. pneumophila, we explored how L. pneumophila-induced PCD is affected by expression of bcl2 in relevant myeloid cell types." (PMID 27973535, 2016). "Both of the bacterial pathogens used in this study interact with myeloid cell death pathways, and this study focuses on the role that cell death controlled by bcl-2 plays during infection." (PMID 27973535, 2016). "As previously reported for Bcl-2 overexpression in U937 cells, Bax/Bak-/- MEFs exhibited a higher infection rate and therefore increased gD staining as compared to their WT counterparts." (PMID 26030884, 2015). "There were increased amounts of Evans blue, apoptotic proteins (caspase-3, -8, and -9 and cytochrome C), and decreased anti-apoptotic proteins (bcl-2) after 2-3 weeks of infection." (PMID 25890054, 2015). "Collectively, these studies provide evidence that MHV68 utilizes a Bcl-2 ortholog to promote infection and survival of developing B cells, and point to a key role for developing B cells in the sustenance of lifelong latency." (PMID 24516386, 2014). "BZLF1, expressed in an early stage of infection, inhibits MHC II-associated invariant chain (CD74) in CD4 T-cells, resulting in downregulation of Bcl-2 and Bcl-xL expression." (PMID 25699089, 2014). "Specifically, we observed that KSHV infection induced the anti-apoptotic protein Bcl-2 by ∼2-fold during the course of infection of shRL cells, and such induction was abrogated in the infection of shNrf2 cells." (PMID 25340789, 2014). "As the infection progressed, caspases 3, 8 and 9 were downregulated compared to the uninfected cultures at 72 hours, surprisingly together with NFκB1, but the Bcl-2 levels were increased." (PMID 25005804, 2014). "Bcl-2 expression increased nearly 1000-fold after infection with HSV-1 or irradiation (p = 0.05) at 24 hours, but the combined effects seemed to compensate this upregulation." (PMID 25005804, 2014). "A down-regulated level of anti-apoptosis factor Bcl-2 was suggested to be responsible for the apoptosis induced by Ad.FLAG-HddSBL infection." (PMID 24983642, 2014). "In Hu-H1 cells, Bax and Bcl-2 expression were significantly increased and decreased, respectively, on and after day three post-infection." (PMID 23805250, 2013). "In the Hu-H1 cells, Bax and Bcl-2 expression were significantly increased and decreased, respectively, on days three and five post-infection." (PMID 23805250, 2013). "After transduction with HoxA9 lentivirus and selection for infection, equal cell numbers of Bcl-2+/+, Bcl-2+/− and Bcl-2−/− cells were seeded in liquid culture containing cytokines and cell numbers were assessed over 9 days." (PMID 24177192, 2013). "In contrast, in Strain V cells, Bax and Bcl-2 expression were significantly decreased and increased, respectively, on and after day three post-infection." (PMID 23805250, 2013). "Pre-infection with Ad-PKG II and treatment with 8-pCPT-cGMP reversed the effect of EGF, causing a marked decrease in Bcl-2 expression." (PMID 24273605, 2013). "IL-7 25 ng/mL increased Bcl-2 expression in HIV-1-infected CD4+ T cells on average 1.5±0.1 fold on day 9 post infection, compared with donor-matched infected untreated tissues (n = 4, p<0.05)." (PMID 23408885, 2013). "Overexpression of Bcl-2 in U937 cells dramatically increased the capability of these cells to sustain a fully productive infection, while protecting against apoptosis induced by HSV-2." (PMID 23922974, 2013).
infection (continued). "Bcl-2, an anti-apoptotic gene, was upregulated about two times in the testis at day 7 post infection as determined by quantitative real-time PCR (relative expression in control v." (PMID 23301002, 2013). "In HIV-1BaL-infected cervico-vaginal tissues IL-7 25 ng/mL increased Bcl-2 expression in uninfected CD4+ T cells on average 2.0±0.3 fold on day 9 post infection (n = 4, p<0.05)." (PMID 23408885, 2013). "HoxB8 and HoxA9 infection induced rapid proliferation of wild type cells but only HoxB8 induced proliferation of Bcl-2−/− cells and permitted the establishment of cell lines." (PMID 24177192, 2013). "In contrast, in the Strain V cells, Bax and Bcl-2 expression were significantly decreased and increased, respectively, on days three and five post-infection." (PMID 23805250, 2013). "A previous report has shown that bcl-2 is down-regulated and apoptosis is increased in macrophages after infection with Mycobacteria bovis BCG." (PMID 24130911, 2013). "Logically, on days three and five post-infection, Bax expression in the Strain V cells was significantly lower than that of the Hu-H1 cells (p<0.001), while Bcl-2 in the Strain V cells was significantly greater than that in the Hu-H1 cells (p<0.001)." (PMID 23805250, 2013). "BHRF1 codes for a homologue of the anti-apoptotic protein Bcl-2 which is highly expressed initially after infection." (PMID 23251493, 2012). "RT-PCR analyses of Bcl2 gene showed that its expression remained unchanged following tissue infection with all of the Candida strains under study." (PMID 22665950, 2012). "This statement is in agreement with our previous findings that there was very little alteration on mRNA and protein levels of Bax and Bcl-2 following infection with NDV." (PMID 22935147, 2012). "Consistent with what was seen with the effect on STAT-5 activation, infection with HIVcs204 inhibited the ability of IL-7 to induce Bcl-2 expression in thymocytes." (PMID 21920046, 2011). "Further analyses demonstrated that upregulation of cleaved caspase-8 and Bcl-2 expression was minimal, but expression levels of cleaved caspase-9, Bax and cytoplasmic cytochrome C increased in both cells after the infection." (PMID 21952623, 2011). "Since we have previously shown that overexpression of Bcl2 can rescue mature osteoclast apoptosis, we examined the impact of AdTIEG infection on levels of Bcl2 gene and protein expression." (PMID 21423731, 2011). "TUNEL staining confirmed that the Tg(bcl2) 535rm DCs were more resistant to apoptosis after infection by L. pneumophila ΔflaA compared to control B6 DCs." (PMID 19521510, 2009). "Following treatment there was a massive drop in CSF leukocyte counts in wt mice but this drop was strongly reduced in Bcl-2-transgenic mice, resulting in about 5 times more leukocytes in the CSF compared to wt mice at 72 h after infection." (PMID 19478887, 2009). "The use of IRES containing vectors resulted in high-level Bcl-2 synthesis during the early stages of infection." (PMID 17904678, 2008). "The relatively higher susceptibility of DCs for MVA-induced cell death is consistent with our recent report that, compared with VV, MVA infection of human MoDCs leads to accelerated decline of intracellular anti-apoptosis genes Bcl-2 and Bcl-L." (PMID 18412969, 2008). "To investigate the mechanism responsible for this difference we measured Mycobacterium-induced mRNA expression of pro-apoptotic (Bad and Bak) and anti-apoptotic (Bcl-2) genes at 6, 18 and 48 h post infection." (PMID 16978419, 2006). "M. leprae induced negligible effect on Bcl-2 mRNA at both infection doses, while Bad mRNA expression appeared to be reduced at MOI-10 but increased at MOI-20." (PMID 16978419, 2006). "This infection induces expression of anti-apoptotic genes, such as BCL-2, as well as chemokines." (PMID 40821191, 2025).